INS (insulin)
Diseases named in the same sentence as INS in open-access papers (continued):
Sharing a sentence is not in itself a finding about the gene and the disease.
Hepatic steatosis (continued). "Taken together, our findings indicate that improvement in insulin sensitivity is not a direct consequence of hepatic FGFR4 silencing but may be mediated by circulating factors such as bile acids and gut hormones or be secondary to improved liver steatosis." (PMID 36586437, 2023). "Likewise, a Fatty Liver Improvement with Rosiglitazone Therapy (FLIRT) study found that rosiglitazone treatment for one year could improve hepatic steatosis and insulin sensitivity, but not liver inflammation and fibrosis." (PMID 31614690, 2019). "However, in the glucose drinking group there was a significant progress in adipose tissue insulin sensitivity, high-sensitivity C-reactive protein (hs-CRP), and in LDL oxidation, suggesting that fructose reduction improves markers of CVD despite the lack of recovery in hepatic steatosis." (PMID 26512643, 2015).
Impaired glucose tolerance (1,370 papers, 2003 to 2026). An abnormal resistance to glucose, i.e., a reduction in the ability to maintain glucose levels in the blood stream within normal limits following oral or intravenous administration of glucose. "Streptozotocin (STZ) treated mice showed reduced body fat, lower insulin levels, impaired glucose tolerance, and increased expression of genes linked to inflammation, lipid metabolism, and apoptosis." (PMID 41977383, 2026). "The SNP rs7903146 affects insulin secretion and β-cell function and the TT allele is associated with progression from impaired glucose tolerance to T2D." (PMID 40170676, 2025). "These symptoms, including polydipsia, weight loss, reduced insulin levels, impaired glucose tolerance, and pancreatic islet damage, were also observed in our experimental results." (PMID 40943103, 2025). "It was shown that insulin secretion was reduced in rats with vitamin D deficiency, and impaired glucose tolerance and insulin secretion were better after single-dose vitamin D subcutaneous injection." (PMID 41517402, 2025). "Together, our findings and the data from the literature suggest that lower expression of ChREBPβ in adipose tissue is associated with reduced insulin sensitivity and impaired glucose tolerance." (PMID 41373582, 2025). "Previous studies have indicated that compared to men, women have an increased risk of impaired glucose tolerance and exhibit greater insulin sensitivity." (PMID 41383644, 2025). "Selective IR in the PP region alone can lead to impaired glucose tolerance and a complete loss of insulin-mediated regulation of HGP." (PMID 40950956, 2025). "It presents as impaired glucose tolerance resulting from deficiencies in insulin secretion, insulin function, or both." (PMID 39104778, 2024). "In diet-induced obese mice, an increase in taxa belonging to Clostridiaceae and Peptostreptococcaceae have also been associated with impaired glucose tolerance and impaired insulin clearance." (PMID 38427692, 2024). "One study found that the offspring of obese mothers on a high-fat diet had impaired glucose tolerance, hyperinsulinemia, and higher fat mass, caused by disrupted insulin signaling and β-cell function in the pancreas." (PMID 39770898, 2024). "This is important since early-phase insulin response is lost in patients with impaired glucose tolerance or early-stage T2DM and is inversely associated with 2-h glucose concentrations." (PMID 38903056, 2024). "This also disrupts glucose regulation, causing elevated fasting blood glucose and insulin levels, impaired glucose tolerance, and hepatic insulin resistance." (PMID 39529694, 2024). "These microbial shifts were associated with impaired glucose tolerance and reduced insulin sensitivity, as evidenced by elevated blood glucose levels and a diminished insulin response during metabolic testing." (PMID 39449954, 2024). "Long-term rapamycin use is linked to impaired glucose tolerance and insulin sensitivity in rodent models." (PMID 38290087, 2024). "We investigated insulin secretion through a GSIS assay to elucidate the mechanism underlying impaired glucose tolerance in cKO mice with β‐cell Parn deficiency." (PMID 39297407, 2024). "In this study, the effect of 12-week daily consumption of magnesium (Mg2+)-containing deep seawater mineral extracts on blood glucose concentration and insulin metabolism-associated indicators was investigated in patients with impaired glucose tolerance." (PMID 39202546, 2024). "High-fat feeding prior to mating led to impaired glucose tolerance and insulin secretion in female offspring, linked to reduced pancreatic islet size and gene expression changes." (PMID 39770898, 2024). "Chlorpyrifos exposure has been associated with increased body mass, adiposity, and impaired glucose tolerance and insulin sensitivity in male C57BL/6 mice, CD-1 mice, and rats when combined with a high-fat diet." (PMID 39767584, 2024).
Impaired glucose tolerance (continued). "Analysis of this mouse model suggested that impaired glucose tolerance resulted from insufficient insulin secretion, attributed to the lack of an increase in islet number associated with pregnancy and reduced insulin sensitivity in maternal tissues." (PMID 38626157, 2024). "While in one study, no major differences of Cav1.3 deficiency were observed on blood glucose and insulin levels upon fasting or a glucose challenge, another study found a hypoinsulinemic phenotype and impaired glucose tolerance." (PMID 37698939, 2023). "Maternal blood glucose levels were inversely associated with insulin sensitivity and β-cell function, which results in a higher prevalence of impaired glucose tolerance in offspring of GDM mothers." (PMID 37626162, 2023). "This loss of β cell mass was accompanied by reduced insulin production and impaired glucose tolerance." (PMID 37189396, 2023). "The treatment of wild–type mice with selenoprotein P was associated with the appearance of impaired insulin sensitivity and impaired glucose tolerance." (PMID 37274345, 2023). "Laboratory studies controlling for sleep quality in healthy adults have found that several days of sleep restriction were sufficient to cause a significant decrease in insulin sensitivity and impaired glucose tolerance." (PMID 36014897, 2022). "Impaired glucose tolerance was associated with impaired insulin secretion after oral glucose challenge." (PMID 35167496, 2022). "Clock misalignment is associated with decreased or increased insulin secretion, impaired glucose tolerance, and an alteration of the pancreatic B-cell function." (PMID 35054894, 2022). "This diet has been linked to increased blood glucose, elevated fasting insulin, impaired glucose tolerance, and heightened HOMA-IR." (PMID 35628485, 2022). "A genetic polymorphism in PPARD (rs 2267668; A/G intron variant) affects insulin sensitivity by modifying skeletal muscle glucose uptake and also predicts the conversion from impaired glucose tolerance to T2DM." (PMID 35205333, 2022). "Palmitic acid was found to be positively correlated with HOMA-IR and markers of hyperlipidemia (e.g., TC, LDL-C, and TC), and inversely correlated with adiponectin, which in turn was associated with impaired glucose tolerance and insulin homeostasis." (PMID 36035400, 2022). "Meanwhile, excess intake of high-fructose corn syrup leads to impaired glucose tolerance due to insulin secretion deficiency." (PMID 35216187, 2022). "These individuals were leaner, had a higher insulin sensitivity, a lower risk for impaired glucose tolerance (IGT) (OR 0,44-0,53 in all cohorts, p<=0.009) and lower fasting glucagon levels." (PMID 36686477, 2022). "In human subjects with normal glucose tolerance, elevated fasting FFA levels were associated with decreased insulin secretion and the risk of developing impaired glucose tolerance." (PMID 35453472, 2022). "Impaired glucose tolerance with low-carbohydrate and/or ketogenic diets was linked to reduced α- and β-cell mass leading to decrease in insulin synthesis and secretion in rodents." (PMID 34578880, 2021). "This is so-called “impaired glucose tolerance” caused by deficiency in insulin secretion responding to elevation of blood sugar or/and insulin resistance occurring much more severely in 70≦ than in 60s." (PMID 34681771, 2021). "DM mice exhibited impaired glucose tolerance and insulin sensitivity which are associated with the development of cognitive decline and poor cognitive performance." (PMID 33603781, 2021). "We next evaluated the insulin tolerance and glucose tolerance of MatOb offspring, as increased body adiposity is associated with decreased insulin sensitivity and impaired glucose tolerance." (PMID 34108935, 2021). "Chronic AAS use also appears to cause higher fasting insulin levels and impaired glucose tolerance and possibly higher levels of VAT; however, research is currently lacking on the effects of AAS use on glucose metabolism." (PMID 33269425, 2021).
Impaired glucose tolerance (continued). "Low testosterone levels are associated with an increased fat mass, reduced insulin sensitivity, impaired glucose tolerance, elevation of triglycerides, and cholesterol and low HDL-cholesterol." (PMID 34039393, 2021). "Our findings are consistent with previous studies showing that offspring from chronically obese dams exhibited impaired glucose tolerance associated with impaired insulin action in metabolically important tissues such as liver and skeletal muscle." (PMID 32407841, 2020). "Loss of one c-Kit allele leads to high fasting blood glucose levels and impaired glucose tolerance, mainly due to compromised insulin secretion in vivo." (PMID 32372975, 2020). "During the oral glucose tolerance test (OGTT), ihs mice exhibit markedly impaired glucose tolerance caused by lower concentrations of plasma insulin, whereas their insulin sensitivity and insulin synthetic ability are found to be normal." (PMID 32502168, 2020). "Impaired glucose tolerance is a common feature associated with human aging, which is caused by defects in insulin secretion, insulin action or both." (PMID 32698539, 2020). "In brief, increasing A/G was associated with lower insulin sensitivity and higher fasting insulin levels in all groups, as well as with greater odds of impaired glucose tolerance in pubertal boys and girls, and of abnormal glycaemia in pubertal boys." (PMID 33013688, 2020). "It is important to note that whilst caffeine can enhance cognitive performance, it is also associated with impaired glucose tolerance and insulin sensitivity, both of which have been associated with impaired cognition in the longer term." (PMID 29425182, 2018). "Activation of FXR by bile acid or administration of an FXR agonist lowered fasting plasma glucose and improved insulin sensitivity in obese and diabetic mice, whereas FXR-deficient mice showed impaired glucose tolerance and decreased insulin sensitivity." (PMID 29416552, 2018). "Of similar interest, Plagl1 or Kcnq1 dysregulation are responsible for impaired glucose tolerance associated with insulin secretion defects." (PMID 30443025, 2018). "This was associated with impaired glucose tolerance, lower fasting insulin levels, lower counts of enteroendocrine cells, fatty liver, and elevated amounts of hepatic triglycerides, cholesteryl esters, and monounsaturated fatty acids." (PMID 30071904, 2018). "Administration of vitamin D improves impaired glucose tolerance and insulin secretion in vitamin D deficient rats by modulating the generation and effects of cytokines." (PMID 28574454, 2017). "Since impaired insulin pulses are also associated with impaired glucose tolerance in T2D, we investigated the effect of the amplitude of insulin pulses on hepatic insulin signaling in the model." (PMID 29118381, 2017). "In mice, fructose-enriched diets were found to cause impaired glucose tolerance with concomitant hepatic triglyceride accumulation and insulin resistance." (PMID 28346369, 2017). "Impaired glucose tolerance is associated with reduced insulin-stimulated glucose disposal and some evidence suggests RT improves insulin sensitivity in middle-age and older adults with T2D." (PMID 26840904, 2016). "Dietary TMAO was shown to exacerbate impaired glucose tolerance, obstruct the hepatic insulin signaling pathway, and cause adipose tissue inflammation in mice fed a high-fat diet." (PMID 26676906, 2016). "In contrast, female rats counteract excessive fat intake by improving their ability to use lipid fuels, which limits adiposity but, as demonstrated in our study, is associated with impaired glucose tolerance and insulin sensitivity." (PMID 26880072, 2016). "We have found that mice homozygous for the tm1b deleted allele have impaired glucose tolerance due to reduced insulin secretion associated with reduced islet mass." (PMID 26432886, 2015).
Impaired glucose tolerance (continued). "The male Afmidtm1b/tm1b mice retain normal insulin sensitivity and the impaired glucose tolerance is likely caused by a defect in both first and second phase insulin secretion as measured in isolated perifused islets." (PMID 26432886, 2015). "Impaired glucose tolerance is usually associated with reduced insulin sensitivity, which was also demonstrated for Tas1r3-/- mice in our study." (PMID 26107521, 2015). "Studies have shown that increased PTH was associated with impaired glucose tolerance and decreased insulin sensitivity." (PMID 25254046, 2014). "17Beta-estradiol treatment reverses the impaired glucose tolerance, hyperglycemia, and reduced insulin release caused by ovariectomy in rats." (PMID 25400333, 2014). "They began by showing that loss of PICK1 led to impaired glucose tolerance and lowered serum levels of insulin." (PMID 23630455, 2013). "These ICA69 KO mice displayed similar glucose metabolic defects as the PICK1 KO mice, with decreased body weight, increased food/water intake, and impaired glucose tolerance due to insulin deficiency." (PMID 23630453, 2013). "N-STZ pregnant females displayed impaired glucose tolerance that is associated with a lower insulin secretion." (PMID 23691181, 2013). "A recent polymorphism in the human Kv1.3 gene that functionally elicits a gain in function has been associated with impaired glucose tolerance, lower insulin sensitivity, and impaired olfactory ability in male homozygous carriers." (PMID 21966386, 2011). "Taken together, telomerase deficiency causes shortened telomere length in pancreatic islets, and impaired glucose tolerance as well as impaired insulin secretion in mice." (PMID 20876939, 2010). "Elevated fasting levels of plasma insulin and impaired glucose tolerance have been widely recognized as major independent risk factors for the development of coronary heart disease." (PMID 17961235, 2007). "Likewise, previous studies have linked the elevated plasma IAA concentration to increased HOMA-IR values and impaired glucose tolerance in children, which is associated with diminished insulin sensitivity." (PMID 40431415, 2025). "We present here the full spectrum of glucose tolerance to assess the ethnic differences in the relationship between beta cell function and IPL, accounting for insulin sensitivity in our associative assessments, and including novel data from those with impaired glucose tolerance (IGT)." (PMID 40768046, 2025). "Altogether, these findings suggest that the association between high maternal folate status and impaired glucose tolerance is complex and may involve multiple glucose-insulin signaling pathways." (PMID 41030891, 2025). "We decided to highlight these findings because the other indicator of impaired glucose tolerance (fasting insulin) was positively associated with the odds of infertility in our data, and this therefore suggests a plausible relationship between impaired glucose tolerance as a whole and infertility." (PMID 37949105, 2024). "Furthermore, the persistence of this impaired glucose tolerance in postpartum was associated with a higher diagnosis term, the use of insulin for the treatment of GDM, the delivery by cesarean section, or the delivery of a macrosomic newborn." (PMID 38618305, 2024). "Defective insulin action and secretion are two major causes of impaired glucose tolerance." (PMID 37914684, 2023). "Since lean body mass is responsible for glucose disposal mediated by insulin, sarcopenia may cause impaired glucose tolerance and IR." (PMID 37919650, 2023). "Hyperthyroidism is associated with impaired glucose tolerance and hyperglycemia, due to elevated glucose absorption through the gastrointestinal tract, increased hepatic glucose output, enhanced adipose tissue lipolysis and reduced insulin turnover." (PMID 36830883, 2023).